SMAD7 (SMAD family member 7)
Diseases named in the same sentence as SMAD7 in open-access papers (continued):
Sharing a sentence is not in itself a finding about the gene and the disease.
cancer (continued). "We successfully optimized our TCM‐derived natural compound formula AANG for the multidrug resistant HCC, which specifically inhibited Smad3 activation but up‐regulated Smad7 expression in both cancer cells and the TME in vitro and in vivo." (PMID 34514726, 2021). "To note, Smad7 is a negative regulator of NF‐κB signalling pathway, which NF‐κB is highly activated in cancer and regulates the p‐glycoprotein expression in HCC." (PMID 34514726, 2021). "Dramatic reduction in Smad7 but activation of Smad3 occurs in many inflammatory disease conditions including cancer." (PMID 34514726, 2021). "We have developed natural compound formula AANG, which is derived from traditional Chinese medicine (TCM) and effectively inhibited Smad3‐dependent cancer progression in mice via suppressing Smad3 but reactivating Smad7 in the TME." (PMID 34514726, 2021). "A different scenario emerges from studies investigating the role of Smad7 expressed by cancer cells." (PMID 33920230, 2021). "Among these, Smad7 modulation for CC therapy remains an intriguing but still open topic, due to the extremely complex role of Smad7 in cancer biology." (PMID 33920230, 2021). "In this article, we review the data about the expression and role of Smad7 in intestinal inflammation and cancer." (PMID 33920230, 2021). "As we have mentioned, Smad7 is a TGFβ1 signaling inhibitor and has been reported to inhibit TGFβ1-induced cancer cell EMT and metastasis." (PMID 33085646, 2020). "To assess the functional consequences of SMAD7 induction by RAC1B for cancer-relevant cellular responses, we performed a series of real-time cell migration assays with a chemokinesis setup following KD/KO or ectopic overexpression of SMAD7." (PMID 32545415, 2020). "Smad7 is a TGFβ1 signaling inhibitor and has been reported to inhibit TGFβ1-induced cancer cell epithelial-mesenchymal transition (EMT) and metastasis." (PMID 33085646, 2020). "SMAD7, a member of SMAD family, is reported to be associated with the development of a variety of cancers." (PMID 32899503, 2020). "In CRC, reduced level of SMAD7 is found to be involved in the process of cancer growth as well as the process of EMT and invasion." (PMID 32899503, 2020). "Taken together, these data highlight a dual role of Smad7 in different types of cancer with anti-tumorigenic or pro-tumorigenic effects according to the cancer biology and site of development." (PMID 31052449, 2019). "TGF-β signaling is pivotal in liver injuries leading to fibrosis, and expression of the negative regulator of TGF-β signaling, Smad7, can modulate liver injury, fibrosis and also cancer development in (for instance) hepatocytes." (PMID 31698731, 2019). "Altogether, our data suggest that exosomal miR-21-5p induces MMT of PMCs and promote cancer peritoneal dissemination by targeting SMAD7." (PMID 30154401, 2018). "As a type of genes located near Smad7 in mice, LncRNA-Smad7 has been reported to inhibit apoptosis of cancer cells with its expression in mammary epithelial cells and BC cell lines." (PMID 30459529, 2018). "Smad7 and Smurf2 have been identified as TGFβ signaling inhibitors that are overexpressed in some types of cancer." (PMID 28431583, 2017). "Smad7 is highly expressed in cholangiocarcinoma and involved in cancer EMT and metastasis and is a potential prognostic cancer marker." (PMID 27974675, 2017). "Here the authors show that in cancer cells TGFβ activates the expression of microRNA-182 that suppresses SMAD7 protein, promoting TGFβ-mediated breast tumour invasion and bone metastasis." (PMID 27996004, 2016).
cancer (continued). "To corroborate that SMAD7 suppression mediates the role of miR-182 in cancer cell TGFβ responses, we treated EpRas cells with a SMAD7 siRNA inhibitor in addition to TGFβ stimulation and miR-182 inhibition." (PMID 27996004, 2016). "In this study, we showed that miR-182 also targets SMAD7 to elevate cancer cell responses to TGFβ during metastasis." (PMID 27996004, 2016). "The assays were repeated in MCF10AT cells as well, and the same changes in EMT markers were observed, suggesting that SMAD7 induction mediates the effects of miR-182 inhibition in cancer cell EMT." (PMID 27996004, 2016). "TGF-β-SMAD7 signaling pathway has been showed to be a key signaling pathway of epithelial-mesenchymal transition (EMT) in cancers." (PMID 27628042, 2016). "In summary, our current findings indicate that FFLZ is a potential therapeutic or dietary supplemental agent for cancer patients and that it functions via the caveolin-1/Smad7/Smurf2-dependent ubiquitin-mediated degradation of TGFR." (PMID 27830743, 2016). "We further found that these cancer cells achieved this via TGFβ-induced expression of miR-182, which suppressed SMAD7 and thus endorsed the extended activation of TGFβ signalling leading to EMT and metastasis." (PMID 27996004, 2016). "Although SMAD7 mRNA was not obviously affected by miR-182, a significant reduction of SMAD7 protein abundance was observed on miR-182 overexpression in these cancer cells." (PMID 27996004, 2016). "Taken together, these data suggest that miR-182 upregulates cancer cell response to microenvironmental TGFβ and bone metastasis by suppressing SMAD7." (PMID 27996004, 2016). "The expression of miR-182 antagonizes the response of SMAD7 to TGFβ and promotes cancer cell EMT, invasion, as well as distant metastasis." (PMID 27996004, 2016). "Depletion of SMAD7 upregulated the effects of TGFβ and reduced the expression of IL-1R1, leading to inhibition of IL-1α induced stellate cell enhancement of carcinoma cell migration." (PMID 27473228, 2016). "This strongly suggests that carcinoma cell migration is induced by IL-1α activation of PSCs, which can be inhibited by SMAD7 depletion." (PMID 27473228, 2016). "The conditioned medium from the co-culture of BxPC-3 cells and SMAD7 silenced PSCs significantly inhibited the migration of carcinoma cells compared to the conditioned medium obtained from the co-culture of BxPC-3 and non-silenced PSCs." (PMID 27473228, 2016). "In particular, it was shown that ectopic expression or deletion of Smad7 in cancer cells can differently regulate tumorigenesis depending on the cell context analyzed." (PMID 24317436, 2013). "Our results are important because many components of the TGF-β signaling pathway are mutated, downregulated, or overexpressed in multiple diseases, such as the TGF-β receptors, R-Smads, Smad4, and Smad7 proteins in a variety of cancer types." (PMID 24386222, 2013). "In this article we review and discuss the available data supporting the role of Smad7 in the modulation of cancer growth and progression." (PMID 24317436, 2013). "High Smad7 is seen in several human malignancies and there is preliminary evidence that Smad7 expression correlates with the clinical prognosis of cancer patients." (PMID 24317436, 2013). "Further work is needed to delineate the mechanisms by which Smad7 exerts its distinct functions on tumorigenesis and to clarify which cancer-related pathways are predominantly affected by Smad7 in the different contexts." (PMID 24317436, 2013). "While activated Smad2/3 complexes promote EMT, the inhibitory Smad7 prevents the transition of cancer cells towards a mesenchymal phenotype." (PMID 21747928, 2011). "The Smurf2 and Smad7 complex ubiquitinates TβRI, a key event resulting in degradation of the receptor and TGFβ resistance in cancer cells." (PMID 14562029, 2003).
cancer (continued). "I-Smads (Smad6 and Smad7) are of key importance for maintaining a proper physiological response to TGF-β and BMP signaling and their deregulation has been linked to a number of different diseases, including fibrosis and cancer." (PMID 38876303, 2024). "Thus, a dual role of SMAD7 has been described in various types of cancer with pro‐tumorigenic or anti‐tumorigenic effects depending on the cancer site and biology." (PMID 36550779, 2023). "Under well oxygenated conditions, SMAD7 is an effective inhibitor of cancer invasion." (PMID 35449150, 2022). "By principal component analysis, we were also able to identify several clusters of the batches with similar 31P-NMR spectra, and preparations with the same 31P-NMR spectrum profile which had similar in vitro activity, as shown by their inhibitory effect of Smad7 in cultured cancer cell lines." (PMID 36678723, 2022). "The SMAD7 gene was downregulated by the polyherbal, which could be positive, since its overexpression is common in many types of cancer, and its abundance is positively correlated with malignancy." (PMID 35625159, 2022). "Furthermore, the pharmacological batch of mongersen used in this study inhibited Smad7 expression in cultured cancer cells." (PMID 36678723, 2022). "Likewise, exosomal miR-21-5p induced the mesothelial to mesenchymal transition of peritoneal mesothelial cells by targeting Smad7 and promoted the peritoneal spread of cancer." (PMID 35173726, 2022). "Therefore, the upregulation of Smad7 is necessary to prevent cancer cells from adversely affecting BMPs." (PMID 34059951, 2021). "In several cell types and cancer cell lines, SMAD7 regulation is induced by JAK/STAT pathway." (PMID 33916615, 2021). "miRNA-182 potentiates TGF-β-induced EMT and cancer cell metastasis by inhibiting SMAD7 expression." (PMID 34059951, 2021). "In this study, high expression of SMAD7 was correlated with poor development of cancer." (PMID 34138687, 2021). "In the present study, Smad7 was identified as a direct downstream target of miR-21; thus, the cellular functions of miR-21 might be related to cancer cell migration and invasion." (PMID 33085646, 2020). "Various studies have suggested different expression of SMAD7 in human cancers, which could either sustain or restrain cancer cell growth." (PMID 32190221, 2020). "Similarly, miR-21 was reported to be highly-expressed in NSCLC, and to further regulate invasion and chemo-sensitivity of the cancer by mediating the SMAD7 gene." (PMID 33061847, 2020). "Various studies have shown the role of SMAD-7 in tumorigenesis of different types of cancer." (PMID 32856881, 2020). "We here review and discuss the role of TGF-β1/Smad7 axis in gut inflammation, fibrosis and cancer." (PMID 33375423, 2020). "The data obtained in this study reveal that RAC1B effectively inhibits TGFβ1-dependent cell motility of mesenchymal subtype carcinoma cells by promoting protein expression of the inhibitory Smad, SMAD7, via intermittent transcriptional induction of the deubiquitinating enzyme, USP26." (PMID 32545415, 2020). "SMAD7 protein is involved in cisplatin-induced apoptosis in human cancers." (PMID 31159834, 2019). "Recent studies have showed that several cellular microRNAs (such as miR-21, miR-182, miR-106b) could regulate the expression of SMAD7 in various cancers." (PMID 31681406, 2019). "Furthermore, Chen and colleagues found that Smad7 retains in the nucleus in some cancer cell lines even after TGF-β treatment, and inhibits TGF-β-induced transcriptional responsiveness by interfering with the R-Smad-Smad4-DNA complex formation." (PMID 31614569, 2019). "Smad7 overexpression attenuates the cancer-promoting effect of miR-520h." (PMID 30158641, 2018). "Meanwhile, recent studies reported that Smad7 could enhance muscle differentiation and play an important role in prevent of cancer cell metastasis." (PMID 29433423, 2018).
cancer (continued). "The possible underlying mechanism might be that MLL2 down-regulated Smad7 expression, which led to the hyperactivation of TGF-β/Smad signaling and the promotion of cancer progression." (PMID 29532228, 2018). "Similarly, a dual role of Smad7 has been described in various types of cancer with pro-tumorigenic or anti-tumorigenic effects according to the cancer site and biology." (PMID 29973939, 2018). "In addition, SMAD7 has been proved to suppress TGF-β/Smad activity by binding SMAD2/3 and prevent their activation upon TGF-β1 stimulation in cancer-associated fibroblasts (CAFs) formation." (PMID 30154401, 2018). "We here review the role of TGF-β1 and Smad7 in intestinal immunity, inflammation, and cancer." (PMID 29973939, 2018). "Smad7 expression is deregulated in many cancers, suggesting that Smad7 might be a target for interfering with the development and progression of human cancers." (PMID 27974675, 2017). "Thus, miR-182 is both a downstream target of TGFβ and a direct suppressor of SMAD7 in these cancer cell lines." (PMID 27996004, 2016). "Silencing of stellate cell expression of SMAD7 was found to suppress the levels of IL-1R1 and reduce the stimulatory effects of IL-1α, thus inhibiting the capacity of pancreatic stellate cells to induce cancer cell migration." (PMID 27473228, 2016). "As expected, SMAD7 overexpression abolished the effects of miR-182 in cancer cell invasion." (PMID 27996004, 2016). "Although it has been well established that SMAD7 mRNA can be activated by TGFβ (refs 16, 29, 30, 35, 36, 37), only very few studies reported the elevation of SMAD7 protein following TGFβ stimulation in cancer cells." (PMID 27996004, 2016). "The suppression of SMAD7 by miR-182 indicated that miR-182 might play a role in cancer cell EMT, migration and invasion." (PMID 27996004, 2016). "Since miR-182 suppressed TGFβ-induced upregulation of SMAD7, we reasoned that this miRNA could be critical for cancer cell responses to TGFβ." (PMID 27996004, 2016). "Accordingly, the two interacting SNPs could affect expression of the two cancer-associated proteins, TGFBR1 and SMAD7, participating in the same TGF-β signaling pathway, but affecting multiple cancer hallmarks." (PMID 27588484, 2016). "Furthermore, depletion of SMAD7 upregulated the effects of TGFβ and reduced the expression of IL-1R1, leading to reduced stellate cell enhancement of carcinoma cell migration." (PMID 27473228, 2016). "The tissue/context-specific effects of Smad7 partially explain the dual roles of Smad7 in cancer." (PMID 25566830, 2015). "Previous studies have demonstrated that the decreased expression levels of TβRI, SMAD3 and SMAD4 may cause cancer cells to escape the growth inhibition of TGF-β1, and the increased expression of SMAD7 may block the inhibitory effects of TGF-β1." (PMID 25295107, 2014). "The first point is that SMAD7 may be differently regulated in various tumors depending on the context analyzed as it has the pro- and anti-tumorigenic effects in different cancer types." (PMID 25289133, 2014). "It would be also useful to study the role of Smad7 in experimental models of metastasis deriving from primary tumors that evolve in situ and more closely resemble the human disease as well as the effect of Smad7 inhibition in cancer cells that constitutively express this protein." (PMID 24317436, 2013). "Deregulation of TGFBR2 expression levels and of the inhibitory SMAD7 could influence the normal cellular homeostasis and also influence cancer progression." (PMID 23951322, 2013). "Increasing evidence indicates that Smad7 is differently expressed in human cancers, and it could either sustain or restrain cancer cell growth." (PMID 24317436, 2013). "The expression of SMAD7 is very low in epithelial tissues, but is up-regulated in several cancers." (PMID 23560096, 2013).
cancer (continued). "However, resistance to TGF-β in cancer may occur through several mechanisms such as reduced expression of TβRI and/or TβRII, mutations or functional inactivation of TβRII, inactivating mutations in Smad2 and Smad4 and overexpression of inhibitory proteins including Smad7." (PMID 16251876, 2005). "A gene array, real-time PCR, and Western blotting of SMAD7 AS-treated cells showed a marked down-regulation of the X-linked inhibitor of apoptosis protein (XIAP), a member of the inhibitor of apoptosis family, which has been implicated in cancer cell migration." (PMID 39001432, 2024). "Moreover, the survival of cancer cells and apoptosis were induced after SMAD7 transduction." (PMID 35449091, 2022). "Besides targeting Smad3, overexpression of Smad7 also effectively inhibit cancer in animal models." (PMID 34514726, 2021). "Moreover, Smad7 ectopic expression reversed the effects of miR-520h upregulation in vitro and in vivo, which was consistent with other reports showing that miRNAs promote cancer cells progression by downregulating Smad731." (PMID 30158641, 2018). "SMAD7 is both a transcriptional target and a negative regulator of TGFβ signalling, thus mediating a negative feedback loop that may potentially restrain TGFβ responses of cancer cells." (PMID 27996004, 2016). "Additionally, because TGFβ induces formation of cancer-associated fibroblasts (CAFs) to promote cancer progression, it is not surprising that Smad7 can block this process." (PMID 25566830, 2015). "Elevated EMP1 inhibits the interference of SMAD7 with SMAD2/3 activity by promoting the binding of VASP to SMAD7, ultimately activating the TGF-β/Smads signaling pathway-induced cancer cell invasiveness." (PMID 41285728, 2025). "The augmented expression of TGFBR2, CDC25A, SMAD7, and RELA and downregulation of p27 are major events in cell proliferation and cancer invasion." (PMID 40761498, 2025). "Most notably, many of these early response alterations in the cancer cells are known pro‐angiogenic transcripts, including ITGA2, CLDN12, SMAD7, MET, KLF4, ID3 and ID1." (PMID 40116596, 2025). "The increased expression of TGFBR2, CDC25A, SMAD7, and RELA and downregulation of p27 are major events in cell proliferation and cancer invasion." (PMID 40755497, 2025). "miR-1269a can regulate the occurrence and development of cancer by targeting downstream genes (CXCL9, SOX6, FOXO1, ATRX, RASSF9, SMAD7, HOXD10, and VASH1)." (PMID 35252180, 2022). "SMAD family member 7 (SMAD7), a member of the SMAD family, has been validated to be referred to cancer progression as a cancer-promoting or suppressing factor." (PMID 35068324, 2022). "As a member of an E3 ligase NEDD4 family, NEDD4L not only targets membrane proteins including ion channels and transporters, but also triggers the degradation of certain proteins involved in cancer signaling pathways such as Dvl2, SMAD2, and SMAD7." (PMID 36618071, 2022). "Cytoscape analysis of gene network revealed important cancer pathways including hub genes at NFGR, MAPK3, and SMAD7 for OS, and hub genes at FOXP1, MAP2K5, FGFR1, and NOTCH2 for DFS." (PMID 31608231, 2019). "We also analyzed a panel of putative cancer-related genes, including CDK8, MITF, SMAD7, KLF12, AG02, CDK14, and BCL-9, but only PTEN expression was shown to be significantly altered by miR-216a overexpression." (PMID 30061175, 2018). "A number of studies have found that microRNAs (miRNAs), including miR-182, miR-181a, and miR-375, promote the suppression of SMAD7 and thereby potentiate TGF-β1-induced effects in cancer cells." (PMID 30093732, 2018). "To our knowledge, we for the first time report here the relationships between SOX7 and Smad7 and open the opportunity to elucidate the role of Smad7 in relation to SOX7 or other SOX members in cancers." (PMID 27188720, 2016). "Silencing of endogenous SMAD7 reduced PSC expression of IL-1R1 and attenuated the effects exerted by IL-1α on the ability of PSCs to stimulate cancer cell migration." (PMID 27473228, 2016).